CD63 (CD63 molecule)
Diseases named in the same sentence as CD63 in open-access papers (continued):
Sharing a sentence is not in itself a finding about the gene and the disease.
cancer (continued). "Calibration curves were generated with two most effective combinations (anti‐CD9/Banti‐CD81 and anti‐CD63/Banti‐CD9), resulting in 103 and 104 times higher sensitivity than the EV concentration in human blood plasma from healthy or cancer patients, respectively." (PMID 33664936, 2021). "In the absence of DSPE-PEG-DSPE, the numbers of both CD63 positive (21.6%) and miR-21 positive (31.0%) EVs were higher in the cancer cells, as compared to those in normal cell-derived EVs." (PMID 33477255, 2021). "Many mutants of RAB31 have been detected in various types of human cancer, and we were very curious to test whether any RAB31 mutant may also induce this localization of EGFR to CD63-positive MVEs." (PMID 32958903, 2021). "Furthermore, when cancer EVs were clustered using DSPE-PEG-DSPE, the percentages of CD63 positive and miR-21 positive EVs drastically increased to 51.7% and 59.0%, respectively." (PMID 33477255, 2021). "Cancer-associated exosomes opt to transport specific transmembrane proteins, including integrins and tetraspanins such as CD9, CD63, CD81, and CD82 that are specifically recognized by target cells, which can explain the high rate of exosomal uptake by cancer-adjacent stromal cells." (PMID 32121073, 2020). "For the specific characterization by flow cytometry and confocal microscopy, different commercial antibodies against selected receptors were used, including the general tetraspanins CD9, CD63 and CD81, and cancer-related receptors (CD24, CD44, CD54, CD326 and CD340)." (PMID 32054015, 2020). "Oral cancer-derived salivary exosomes significant increase in the expression of CD63 and decrease in the expression of CD9 and CD81, which could serve as an indicator for cancer, even in the early stages of the disease." (PMID 30954079, 2019). "The MDA-MB-231 cancer cell line expressing the exosomal CD63-red fluorescence (RFP) fusion protein was generated to noninvasively visualize exosome transfer into cancer cells and macrophages." (PMID 29484119, 2018). "The 5-year OS rates of patients with and without CD63 expression in cancer cells were 51.8% and 80.9%, respectively." (PMID 30222750, 2018). "Patients with CD63-positive cancer cells showed significantly worse OS than those with CD63-negative cancer (log–rank; p<0.0001)." (PMID 30222750, 2018). "Patients with CD63-positive cancer showed worse prognosis than those with CD63-negative cancer in this study." (PMID 30222750, 2018). "They analyzed the expression of three exosomal markers (CD9, CD81, and CD63), showing a mean concentration higher for CD63 and lower for CD9 and CD81 between cancer patients and healthy individuals, although significant statistical differences were observed only for CD81 levels." (PMID 29890622, 2018). "The expression of CD63 was reduced in all three cell lines following 1 h CBD treatment, thus confirming the NTA results, showing significant reduction in exosome biogenesis in response to CBD treatment in HEPG2, PC3 and MDA-MB-231 cancer cells." (PMID 30150937, 2018). "But other proteins like CD81, CD63 and ALIX showed a dramatic difference between the two groups and also differed significantly from the MDA-231 derived exosomes, hinting towards a HepN mediated cancer cell transformation." (PMID 29137633, 2017). "Only 6 carcinomas (12.2%) were evaluated as CD63 negative, but 43 carcinomas (87.8%) were CD63 positive." (PMID 21521534, 2011). "We seek to know how metformin induces exosome biogenesis and secretion in cancer cells; and found that the mRNA level of genes related to exosome biogenesis and secretion such as Alix, Rab27b, CD81, CD63, and Lamp-2 concomitantly with CD63 protein level up-regulated in cells treated with metformin." (PMID 38627767, 2024).
cancer (continued). "Thus, we further aimed to compare the binding efficiencies of annexin A5 and GlaS proteins to PS-exposing sEVs and m/lEVs, identified by CD63 or annexin A1 positivity, respectively, derived from cancer and non-cancerous cells using single EV flow cytometry." (PMID 36992223, 2023). "However, we hypothesized that the upregulation of CD63+-EVs and platelet markers (CD41 and CD61)-positive EVs might not be an AD-specific pathology but common in various diseases such as cancers." (PMID 35350978, 2022). "So far, very few studies have investigated three tetraspanins (CD63, CD9, and CD81) together in clinical settings; therefore, it is still unclear whether the level of CD9, CD63, or CD81 correlates with different types of cancers." (PMID 35757760, 2022). "However, we also identified a distinct cluster of cells that we recognised as “cancer” because of genetic aberrations parallel to CD63 basophil marker expression, while not being positive for other canonical basophil markers (e.g., CD123)." (PMID 34948016, 2021). "Labelling CD63-targeting antibody with Alexa Fluor 647 and anti-HER2 antibody with Alexa Fluor 488 enabled imaging with TIRF and simultaneous dual colour PALM/dSTORM for breast cancer cell line-derived EVs alone, as well as upon interaction with non-cancer cells." (PMID 32002172, 2020). "A multitude of evidence revealed that distinct exosomal proteins, e.g., Rab, GTPases, ESCRT, CD9, CD81, CD63, flotillin, TSG101, ceramide, Alix, tetraspanins, and integrins, could be used for cancer detection and consideration of clinical outcomes in cancer patients." (PMID 33168028, 2020). "Moreover, macrophages were utilized to internalize the EVs tagged by anti-CD9 and CD63 and were not allowed to promote cancer progression." (PMID 31428232, 2019). "We observed increased CD63 expression in the cortex area of LNs of exosome-injected mice (6.75% ± 1.18%) compared with LNs of PBS-injected mice (0.53% ± 0.22%) (P = 0.0001), suggesting that cancer exosomes are involved in creating a microenvironment favorable to LN metastasis." (PMID 29484119, 2018). "Therefore, the localization of CD63, which is regulated by RPN2, might contribute to cancer malignancy." (PMID 24884960, 2014). "However, this approach, based on species‐specific reactivity, would not be applicable to detecting cancer‐derived EVs in circulation in humans as many other cell types also secrete human CD63+ EVs into the circulation and such EVs would thereby confound the results." (PMID 35923105, 2022). "Thus, EV CD9/CD63 expression ratio, but not EV physical characteristics, may help differentiate NSCLC patients from cancer-free high-risk individuals." (PMID 35461372, 2022). "However, more importantly, as CD63 and CD9 are also expressed on the surface of EVs released from different cell types, the study of their plasmatic levels could allow obtaining information on the organism's response to the presence of cancer." (PMID 34935096, 2022). "sEV enrichment was verified by transmission electron microscopy and western blotting using antibodies against ALIX, TSG101, CD63, CD81, CD9 (sEV markers), and also against GRP94 (negative control), HSP70 (cancer biomarker), and PD-L1." (PMID 37973956, 2024). "We found that CD9 was co-expressed with CD63-enriched UEVs, but not the CD47, which is over-expressed on EVs derived from cancer cells and involved in cancer metastasis." (PMID 34349163, 2021). "Exosomes derived from MSCs express “CD63, CD9 and CD81” to elicit TRAIL-mediated apoptosis in cancer cells in a dose-dependent fashion without cytotoxicity to human bronchial epithelial cells." (PMID 32957534, 2020). "Notably, while tetraspanins were often used as markers for sEVs, significant signals in CD63 and CD9 were detected in cancer cell-derived m/lEVs, suggesting that these molecules are not unique markers for sEVs, as the MISEV 2018 guidelines stated." (PMID 36992223, 2023).
cancer (continued). "Materials and methods: A novel protein array based on biotin-labelled anti-tetraspanin (CD9, CD63 and CD81) antibodies specific for exosomes in general enabled capture of exosomes from crude human donor plasma and MV preparations from stable isotope-labelled cancer cells and synovial fluid." (PMID 26082317, 2013).
infection (107 papers, 2008 to 2025). The state of being infected such as from the introduction of a foreign agent such as serum, vaccine, antigenic substance or organism. "Delta variant infection of JEG-3 cells significantly increased CD63 + vesicle production—not only in infected cells but also in neighboring bystander cells." (PMID 40630515, 2025). "Previous studies from our laboratory have found that infection with HSV-1(F) increases the release of CD63+ extracellular vesicles (EVs) (29, –, 32)." (PMID 40990523, 2025). "Recently, it has been reported that CD63+ EVs induced during HSV-1 productive infection exhibit antiviral effects." (PMID 40649956, 2025). "CD63 is a well-established marker of EVs generated through secretory autophagy; thus, we examined CD63 expression and vesicle production following infection." (PMID 40630515, 2025). "An ortholog (Tsp29Fb) of the tetraspanin CD63 that interacts with the viral E protein was identified, and its blockade reduced mosquito cell infection." (PMID 39754219, 2025). "CD63 quantification confirmed the presence of EVs from neuronal samples and that infection with T. gondii decreases CD63+ EV concentration (p < 0.05)." (PMID 40523037, 2025). "The CD63:BlaM-equipped virus stocks were also used to determine their titers after Raji cell infection." (PMID 40444990, 2025). "In the ZIKV context, infection alters the expression profile of several tetraspanins, including the upregulating CD63, which localizes to viral replication complexes." (PMID 41157594, 2025). "Intracellular levels of CD63 are usually reduced during HSV-1(F) infection, as the protein is exocytosed in EVs in large quantities (29, –, 31)." (PMID 38470056, 2024). "When analyzing equal volumes of EV preparations by western blot, we showed that the EV markers CD63 is enriched during OV infection, thus confirming the results obtained by flow cytometry." (PMID 39492948, 2024). "Consistent with this, the inhibition of 12-LOX with CDC after infection with WT Sp infection resulted in a similar decrease in PMN CD63 surface expression (“CDC”)." (PMID 39120139, 2024). "The CD63 signal obtained suggests an increase in the quantity of exosomes under infection conditions." (PMID 36851578, 2023). "EVs isolated from the infection model showed positive staining for tetraspanin-30 (CD63) surface protein, with median size average of 147 nm and range consistent with characteristics of endocytic origin, i.e., exosomes." (PMID 36985125, 2023). "To further determine the region important for VSVΔG*-LUJV/GP infection, we tested CD63 mutants having chimeric human-mouse CD63 LEL regions." (PMID 35164564, 2022). "To investigate which region of human CD63 is important for VSVΔG*-LUJV/GP infection, we generated BHK cell lines stably expressing chimeric human-mouse CD63 proteins and compared their susceptibilities to the viruses." (PMID 35164564, 2022). "This is consistent with LAMP3/CD63’s role shown in previous literature where knockdown of LAMP3/CD63 impeded VSV-LUJV infection of endothelial cells, and LAMP3 knockdown in lung epithelial cells resulted in reduced replication of influenza virus." (PMID 36350153, 2022). "LAMP3/CD63, with other tetraspanins, also alters virus-cell fusion and cell-cell spread of infection." (PMID 36350153, 2022). "CD63 siRNA-treated HeLa, HaCaT, and primary keratinocytes exhibited decreased infection by more than 50%, while rescuing CD63 was sufficient to re-establish the viral infectivity rate." (PMID 34769038, 2021). "We also show that the EV-enriched tetraspanin CD63 regulates the release of EVs and Zika viral genomes and capsids following infection." (PMID 34190582, 2021). "CD63 on progeny HIV-1 surface was also found to interfere with infection, and this interference was extended to other tetraspanins (CD9, CD81, CD82, and TSPAN7)." (PMID 34769038, 2021). "As discussed in previous studies, exosomal CD63 was also involved in multiple processes of inflammatory responses to infection." (PMID 34645935, 2021).
infection (continued). "For in vivo derived virus, there were no drastic differences in the types of particles secreted versus uninfected tissue homogenate, but infection globally increased the number of CD63+ and/or nucleic acid positive events." (PMID 34959531, 2021). "Since these transcripts were measured at 48 h during early infection, it is possible the virus requires CD63 during a stage of the replication cycle." (PMID 34190582, 2021). "Cluster of differentiation 63 (CD63), a four-transmembrane glycoprotein in the subfamily of tetraspanin, has been widely recognized as a gateway from the infection of foreign invaders to the immune defense of hosts." (PMID 32793193, 2020). "Tetraspanins of CD9 and CD63 were readily detectable in serum exosomes isolated at various time points post infection." (PMID 33396228, 2020). "One hour after infection, we used flow cytometry to quantify CD63 mean fluorescence intensity (MFI) on the neutrophil surface, which is proportional to the level of primary granule release." (PMID 31822588, 2019). "Knockdown of CD63 displayed a reduction of infection by more than 50% and CD9 knockdown resulted in a strong inhibition of about 90%, which was comparable to results obtained by CD151 siRNAs." (PMID 30279342, 2018). "Our functional analysis of CD63+ve exosomes revealed that exosomes derived from HIV-1 infected DCs successfully transmitted infection to T cells and induced 4–5 fold increased HIV-1 replication compared to cell free HIV-1 virus." (PMID 29093555, 2017). "The CD63-luciferase cell line was then used to monitor exosome secretion upon EV71 or CA16 infection." (PMID 28910400, 2017). "To extend these observations we analysed the role of CD63 in infection of two other oncogenic HPV types: HPV18 and HPV31." (PMID 27578500, 2016). "Our earlier studies showed that anti-CD63 monoclonal antibody treatment 30 min prior to and during infection markedly reduced HIV-1 replication in MØ." (PMID 24507450, 2014). "Attenuation correlated with increased oxidants in macrophages in response to DKO infection and enhanced labeling of lysosomal markers (CD63 and rab7) on DKO phagosomes." (PMID 22574140, 2012). "ASFV virions stained with an antibody against major capsid protein p72 colocalized at high percentages with EEs within the first 30 min of infection, while colocalization with CD63, Rab7 and Lamp1 was very low at this time point." (PMID 23133661, 2012). "If HSV-2 exploited MVBs and/or late endosomes for assembly or release of virions, and if Nedd4 and UL56 were involved in the process, a greater amount of Nedd4 and UL56 should colocalize with CD63 as the infection proceeds." (PMID 19835589, 2009). "We found that virus particles started to colocalize with internal CD63 at the cell periphery already 3 hours after infection." (PMID 18836553, 2008). "Specifically, the infection profile of the Lujo virus pseudotype was better explained by the mRNA levels of the NRP2 receptor (P < 0.001) than those of the downstream entry factor CD63." (PMID 39747691, 2025). "Furthermore, infection causes a shift of WGA-FITC distribution towards MVBs, as more overlap of WGA-FITC signals with those for CD63 is observed in infected than in uninfected fibroblasts." (PMID 39334915, 2024). "FCoV-infected CRFK-derived EVs presented significantly elevated expression of Alix (∗∗p ≤ 0.01), TSG101 (∗∗∗p ≤ 0.001), and CD63 (∗∗p ≤ 0.01) at 48 h infection and significantly increased expression of TSG101 (∗p ≤ 0.05) at 72 h infection relative to the control EVs, respectively." (PMID 39091390, 2024). "Interestingly, for the extracellular vesicle fraction, we observed that SIRT-1 knockdown decreased the release of CD63-positive EVs during EV-D68 infection compared to the scramble control." (PMID 37850626, 2023). "Infection results in an increase in CD63 in the extracellular vesicles." (PMID 37850626, 2023).
infection (continued). "Interestingly, CD63 has been shown to participate in the infection of several viruses, demonstrated using mostly inhibitory antibodies or RNA interference technology." (PMID 37198427, 2023). "Contribution of amino acid residues at positions 141 to 150 in CD63 to VSVΔG*-LUJV/GP infection." (PMID 35164564, 2022). "Importance of the phenylalanine at position 143 in human CD63 for VSVΔG*-LUJV/GP infection." (PMID 35164564, 2022). "CD63 and uroplakin members have been suggested to have similar functional properties in S. japonicum, although the exact roles for uroplakins, either in the infection process or in pathogenesis, is still unkown and further research is needed." (PMID 35073344, 2022). "Hence, lowering tetraspanin CD81 and/or CD63 expression or blocking their activity during early infection seems to be a promising strategy to limit reverse transcription, genomic integration, and ultimately viral replication." (PMID 34769038, 2021). "Since we observed reduced virus titers upon CD63 knockdown, CD63 may play temporally distinct functions, supporting trafficking during virus assembly and egress late in infection." (PMID 32041945, 2020). "Similarly, depletion of the CD63-positive exosome population in herpes simplex virus-1-infected cells enhanced infection." (PMID 30702421, 2019). "LCMV GPC-mediated infection, entry, and fusion were not affected by the absence of Lamp1, and loss of CD63 did not impair LCMV GPC-mediated infection." (PMID 29295909, 2018). "siRNAs targeting CD151 and CD63 served as a control for impaired infection." (PMID 30279342, 2018). "Interestingly, the endosomally concentrated tetraspanin CD63 was recently identified as promoting fusion and infection by the Old World arenavirus, Lujo virus (LUJV)." (PMID 29295909, 2018). "Likewise, bead-based flow cytometric analysis also revealed that the release of CD63/CD81+ host cell MVs also increased upon infection." (PMID 29132302, 2017). "We have previously shown that HIV-1-infected cells have increased levels of cytosolic unprocessed CD63, while exosomes from HIV-1-infected cells contain increased levels of glycosylated CD63, indicating that infection results in increased CD63 production or exosome biogenesis." (PMID 27872619, 2016). "Although most of the published literature relies on these proteins, there may be varying levels of certain markers including TSG101, Alix, and CD63 following an infection." (PMID 26539170, 2015). "However, in the context of a Mm infection, neutrophils from control animals or animals treated with imatinib displayed increased surface expression of CD66b and CD63 relative to uninfected controls." (PMID 25822986, 2015). "This colocalization could be observed throughout the replication cycle in HFFs and ARPE-19 cells and was decreased with the reduction of the CD63 signal in HFFs late in infection." (PMID 24517969, 2014). "Virus localized to CD63-positive structures, presumably MVBs, starting at 60 min post-infection." (PMID 25233119, 2014). "The amount of CD63 that was co-localised with E. coli DH5α phagosomes increased at the 15 minute, 30 minute and two hour time-points, to an amount that was maintained at four hours after infection (ECOL)." (PMID 21426584, 2011). "However, at 2h post-infection, the number of CD63-positive phagosomes was significantly higher in cells infected with WT BCG, compared to cells infected with r-BCG PGL-1." (PMID 20975946, 2010). "Notably, RDV was accompanied by Rab5-, Rab27a-, or CD63-involved exosomes into the sieve tube cells of rice phloem after viruliferous leafhoppers feeding and then spread through rice phloem to establish initial infection." (PMID 34214032, 2021). "Transient platelet activation was observed at 6 h post infection characterized by a significant increase of complement C3c, indicating opsonization, the platelet aggregation factor fibrinogen, and the activation markers CD63 and CD62P on the surface of platelets." (PMID 33519798, 2020).